PDCL3 (phosducin like 3)
Description:
Acts as a chaperone for the angiogenic VEGF receptor KDR/VEGFR2, increasing its abundance by inhibiting its ubiquitination and degradation. Inhibits the folding activity of the chaperonin-containing T-complex (CCT) which leads to inhibition of cytoskeletal actin folding. Acts as a chaperone during heat shock alongside HSP90 and HSP40/70 chaperone complexes (By similarity). Modulates the activation of caspases during apoptosis.
Synonyms: PhLP2A; VIAF1; HTPHLP; PHLP3; VIAF
Tractability: Small molecule: a structure with a bound ligand is known. PROTAC: ubiquitination databases record sites on it; its protein half-life has been measured.
Gene: Protein-coding gene on chromosome 2 (100,562,968 to 100,577,472, forward strand). Ensembl gene ENSG00000115539.
Subcellular location: Cytoplasm; Cytoplasm, perinuclear region; Endoplasmic reticulum
Subcellular location (Human Protein Atlas): Cytosol; Nucleoplasm
Gene Ontology:
Molecular function: protein binding; protein folding chaperone; vascular endothelial growth factor receptor 2 binding
Biological process: actin cytoskeleton organization; angiogenesis; negative regulation of protein folding; negative regulation of ubiquitin-dependent protein catabolic process; positive regulation of angiogenesis; positive regulation of endothelial cell proliferation; positive regulation of gene expression; protein folding; protein stabilization; regulation of peptidyl-tyrosine phosphorylation
Cellular component: cytoplasm; cytosol; endoplasmic reticulum; nucleoplasm; perinucleolar compartment; perinuclear region of cytoplasm; protein-containing complex
Genetic constraint (gnomAD): Loss-of-function variants: 23 observed, 26.41 expected, observed/expected ratio (o/e) 0.87, 90% interval 0.63 to 1.23. The upper end of that interval is the gene's LOEUF score, 1.23, which puts it in group 5 of 6, group 1 being the genes least tolerant of losing a copy. Missense variants: 238 observed, 285.9 expected, observed/expected ratio (o/e) 0.83, 90% interval 0.75 to 0.93. Synonymous variants: 79 observed, 102.39 expected, observed/expected ratio (o/e) 0.77, 90% interval 0.64 to 0.93.
Homologues: Orthologues: chimpanzee PDCL3 (99% identical), macaque PDCL3 (96% identical), pig PDCL3 (90% identical), rabbit PDCL3 (90% identical), mouse Pdcl3 (90% identical), guinea pig PDCL3 (88% identical), rat Pdcl3 (87% identical), tropical clawed frog pdcl3 (78% identical), zebrafish PDCL3 (62% identical). Paralogues in human: PDCL2 (59% identical), PDCL (28% identical), PDC (24% identical), TXNDC9 (24% identical).
Diseases named in the same sentence as PDCL3 in open-access papers:
PDCL3 is named in the same sentence as 25 diseases in open-access papers, as found by Europe PMC text mining. Sharing a sentence is not in itself a finding about the gene and the disease. The quoted sentences say what the papers report.
glioma (3 papers, 2023 to 2025). A benign or malignant brain and spinal cord tumor that arises from glial cells (astrocytes, oligodendrocytes, ependymal cells). "The promotive role of PDCL3 in hepatocellular carcinoma and glioma has been reported previously, and its diagnostic and prognostic value has been confirmed in these two diseases." (PMID 40709189, 2025). "The results reflected that PDCL3 expression was significantly associated with the pathological grade and prognosis of glioma patients." (PMID 37006287, 2023). "More importantly, the association of PDCL3 with the infiltration of immune cells, immunomodulatory genes, immune checkpoints, cancer stemness and angiogenesis suggested that PDCL3 may regulate the glioma immune landscape." (PMID 37006287, 2023). "The association of PDCL3 with the infiltration of immune cells, immunomodulatory genes, immune checkpoints, cancer stemness and angiogenesis suggested that PDCL3 may be involved in regulating the immune landscape of the glioma microenvironment." (PMID 37006287, 2023). "In this study, the authors conducted univariate and multivariate Cox regression analyses in combination with common clinicopathological characteristics and ultimately determined that PDCL3 acted as a potential prognostic biomarker of glioma." (PMID 39744629, 2024). "Due to the functional enrichment of PDCL3, which is frequently involved in cell-to-cell interactions and immune-related functions, we further investigated the correlation of PDCL3 with the glioma immune landscape." (PMID 37006287, 2023). "The satisfactory prognostic efficiency of this nomogram also demonstrated the value of PDCL3 in predicting glioma prognosis." (PMID 37006287, 2023). "Here, two single-cell sequencing databases, CancerSEA and TISCH, were used to further verify the function and expression of PDCL3 in glioma." (PMID 37006287, 2023). "Especially in gliomas, PDCL3 expression revealed a positive correlation with M1 macrophages, M2 macrophages, CD4+ T cells, CD8+ T cells, Tregs, and dendritic cell infiltration." (PMID 37006287, 2023). "At the beginning of this study, we identified that PDCL3 was upregulated in various cancer tissues and strongly correlated with poor prognosis in glioma patients." (PMID 37006287, 2023). "The KM survival curve indicated that the OS of glioma patients in the low PDCL3 groups was significantly better than that in the high PDCL3 groups." (PMID 37006287, 2023). "In summary, high expression of PDCL3 mediates the malignant progression of glioma cells, and it is a novel oncogene in glioma." (PMID 37006287, 2023). "This also explains why patients with high levels of PDCL3 have poor prognosis from the perspective of the glioma immune microenvironment." (PMID 37006287, 2023). "The results revealed that PDCL3 is upregulated in multiple cancers and acts as a potential prognostic biomarker of glioma." (PMID 37006287, 2023). "Although there is insufficient experimental evidence to prove how PDCL3 directly regulates the immune landscape, our results confirmed the high correlation between PDCL3 expression and glioma immunosuppression." (PMID 37006287, 2023). "The abnormal expression of PDCL3 is not only closely related to the clinical characteristics, prognosis and tumor immune microenvironment of glioma but is also involved in promoting the malignant progression of glioma cells." (PMID 37006287, 2023). "Focusing on the role of PDCL3 in the glioma vascular microenvironment, our study complements previous studies." (PMID 37006287, 2023). "Second, the effect of PDCL3 on glioma immunosuppression and the anti-PD-1 immunotherapy response still needs to be further verified in vitro and in vivo." (PMID 37006287, 2023). "To clarify the function of high PDCL3 expression in glioma cells, we performed a series of cell biology experiments." (PMID 37006287, 2023). "In this study, we demonstrated that PDCL3 expression was significantly correlated with glioma angiogenesis and cancer stemness." (PMID 37006287, 2023).
glioma (continued). "First, we constructed the stable glioma cell lines U251 and U87-MG with low expression of PDCL3 by RNA interference (RNAi) and tested its interference efficiency by Western blotting and qRT-PCR." (PMID 37006287, 2023). "The results of single-cell transcriptome sequencing analysis perfectly supported our previous conclusions and provided a macroscopic landscape of PDCL3 in glioma." (PMID 37006287, 2023). "In this study, we reported a novel prognosis-related biomarker, PDCL3, and its pathological role in glioma for the first time." (PMID 37006287, 2023). "To better understand the functional effects of upregulated PDCL3 in gliomas, we investigated it from the perspectives of epigenetic modification, gene mutation, gene function and protein function by analyzing mult-omics data." (PMID 37006287, 2023). "As a focal point involved in the vascular microenvironment and the immune microenvironment, the regulatory mechanism of PDCL3 in the glioma microenvironment deserves further exploration in the future." (PMID 37006287, 2023). "Knockdown of PDCL3 decreased the proliferation, invasion and migration of glioma cells, which impled the oncogenic role of PDCL3." (PMID 37006287, 2023). "As the WHO grade of glioma samples increased continuously, the expression level of PDCL3 also showed a corresponding upregulated trend." (PMID 37006287, 2023). "In the cohort composed of 94 human glioma tissues, the mRNA expression of PDCL3 in WHO grade IV glioma was significantly higher than that in WHO grade II or WHO grade III glioma, and patients with higher PDCL3 mRNA expression had poorer survival times." (PMID 37006287, 2023). "Consistent results from multiple medical centers, multiple public datasets and multiple different detection methods fully demonstrated the reliability and stability of PDCL3 as a prognosis-related biomarker in glioma." (PMID 37006287, 2023). "In this study, we used an IP-MS assay to explore proteins interacting with PDCL3 in glioma cells." (PMID 37006287, 2023). "In conclusion, PDCL3 is a novel oncogene and can be adopted as a biomarker with value in assisting clinical diagnosis, predicting patient outcomes and assessing the immune landscape of the tumor microenvironment in glioma." (PMID 37006287, 2023). "Consistent results from xCELL, MCPcounter and EPIC showed that the degree of endothelial cell infiltration in the PDCL3 high group was significantly higher than that in the low group, which suggested that gliomas with high PDCL3 were often accompanied by more angiogenesis." (PMID 37006287, 2023). "In particular, its high correlation with IL-10RB and TGFRB suggested that PDCL3 may be involved in the immunosuppression of glioma." (PMID 37006287, 2023). "In addition, the PDCL3 high subgroup had significantly higher immune, stromal and ESTIMATE scores, which also indirectly implied the possible influence of high PDCL3 expression on remodeling the immune microenvironment during glioma development." (PMID 37006287, 2023). "Similar results suggested that PDCL3 may achieve its functions by interacting with CCTs in glioma cells." (PMID 37006287, 2023). "In summary, this study elucidated that PDCL3 is upregulated in various types of human cancers and may serve as a novel prognostic biomarker in gliomas." (PMID 37006287, 2023). "This implies that PDCL3 may also be involved in the regulation of glioma stem cell perivascular niches." (PMID 37006287, 2023). "Finally, although this study aims to reveal PDCL3 as a novel prognostic marker of glioma from multiple perspectives, more mechanisms and regulatory details should be explored in depth." (PMID 37006287, 2023). "Glioma stem cells and angiogenesis, as independent factors in the remodeling of the glioma immune microenvironment, were also explored for their relationship with PDCL3 expression." (PMID 37006287, 2023). "Furthermore, PDCL3 interference also decreased the proliferation, invasion and migration of glioma cells." (PMID 37006287, 2023).
glioma (continued). "From functional enrichment analysis of genes and proteins, we found that upregulated PDCL3 may not only maintain the malignant biological behavior of glioma cells but also be involved in remodeling the tumor microenvironment." (PMID 37006287, 2023). "Moreover, we also examined the mRNA and protein expression levels of PDCL3 in our glioma tissue cohort and tissue microarray by qRT-PCR and IHC assays and performed survival analysis with the corresponding clinical data." (PMID 37006287, 2023). "To further identify whether PDCL3 can be qualified as a prognostic predictor of glioma, we conducted univariate and multivariate Cox regression analyses in combination with common clinicopathological characteristics." (PMID 37006287, 2023). "Taken together, these results strongly imply that PDCL3 may play a critical role in glioma immunoregulation." (PMID 37006287, 2023). "This means that PDCL3 may be involved in the infiltration of T cells and macrophages, especially their immunosuppressive types, in gliomas." (PMID 37006287, 2023). "Finally, we observed that high PDCL3 expression was associated with poor overall survival (OS) and progression-free survival (PFS) in eight different types of cancer, with the most significant relationship being glioma." (PMID 37006287, 2023). "This function of PDCL3 may lead to poor prognosis of gliomas." (PMID 37006287, 2023). "In the glioma tissue microarray cohort, the protein expression of PDCL3 in WHO II grades was significantly lower than that in WHO III and WHO IV grades, and patients with lower PDCL3 protein expression had a better prognosis." (PMID 37006287, 2023).
hepatocellular carcinoma (3 papers, 2023 to 2025). A malignant tumor that arises from hepatocytes. "Our study suggests that elevated PDCL3 expression in hepatocellular carcinoma is associated with poorer prognosis and may serve as a potential diagnostic biomarker for LIHC." (PMID 38494503, 2024).
colon adenocarcinoma (2 papers, 2023 to 2025). "On the other hand, PDCL3 expression was negatively correlated with MSI in GBMLGG (r = -0.3073), LGG (r = -0.0920), COAD (r = -0.1861), colon adenocarcinoma and rectum adenocarcinoma (COADREAD, r = -0.1806), and KIPAN (r = -0.1246)." (PMID 40709189, 2025).
thyroid cancer (2 papers, 2019 to 2025). "In contrast, a negative correlation was observed between PDCL3 expression and TMB in thyroid carcinoma (THCA, r = -0.1158)." (PMID 40709189, 2025).
uterine corpus endometrial carcinoma (2 papers, 2023 to 2025). A endometrial carcinoma (disease) that involves the body of uterus. "In uterine corpus endometrial carcinoma (UCEC), PDCL3 expression positively correlated with Th2 cells but was inversely correlated with NK CD56bright cells, NK cells, pDC, and Effector memory T cells (Tem)." (PMID 40709189, 2025).
brain tumors (1 paper, 2023). "In addition, among multiple human cancer cell lines, PDCL3 expression in brain tumors was also relatively high." (PMID 37006287, 2023).
breast carcinoma (1 paper, 2024). "Additionally, analysis using the CPTAC dataset in UALCAN revealed elevated PDCL3 protein expression in breast cancer, ccRCC, UCEC, LUAD, PAAD, and GBM." (PMID 38494503, 2024).
colorectal cancer (1 paper, 2025). A primary or metastatic malignant neoplasm that affects the colon or rectum. "The expression of PDCL3 in colorectal cancer was also extracted to construct a prognostic model, which effectively predicted the overall prognosis of patients." (PMID 40709189, 2025).
liver cancer (1 paper, 2024). An epithelial or non-epithelial malignant neoplasm that arises from the liver. "PDCL3 protein expression in liver cancer and adjacent tissues was examined through immunohistochemistry and immunofluorescence experiments." (PMID 38494503, 2024). "Immunohistochemical experiments also indicated the same trend, with both IRS scores and H-Score scores showing significantly higher PDCL3 expression levels in liver cancer tissues compared to adjacent tissues." (PMID 38494503, 2024). "Immunofluorescence and immunohistochemistry experiments indicated significantly higher PDCL3 protein expression levels in liver cancer compared to adjacent normal tissues, consistent with PDCL3 expression analysis results in public databases." (PMID 38494503, 2024). "Immunofluorescence experiments confirmed differential distribution of PDCL3 protein in liver cancer tissues and adjacent tissues, with higher PDCL3 protein distribution in liver cancer tissues." (PMID 38494503, 2024). "To further confirm PDCL3’s role in liver cancer development, we modulated PDCL3 gene expression in liver cancer cells via retroviral transfection and investigated PDCL3’s impact on liver cancer cell biological behavior." (PMID 38494503, 2024). "Finally, although this study reveals PDCL3 as a novel prognostic marker for liver cancer from multiple perspectives, further exploration is needed to understand its mechanisms and regulatory details." (PMID 38494503, 2024). "This suggests that PDCL3 may play a promoting role in liver cancer occurrence and development." (PMID 38494503, 2024).
malignant glioma (1 paper, 2023). A grade III or grade IV glioma arising from the central nervous system. "This is the first comprehensive evaluation of PDCL3 expression and its related functions and mechanisms possibly underlying carcinogenesis in patients with malignant glioma." (PMID 37006287, 2023). "However, the underlying role of PDCL3 in human malignant cancers, especially in malignant gliomas, is unclear." (PMID 37006287, 2023). "However, the pathological role of PDCL3 in human cancers has not been investigated, and a comprehensive study on PDCL3 expression, prognostic value, and the underlying mechanisms across cancers, especially in malignant glioma, needs to be performed." (PMID 37006287, 2023).
uveal melanoma (1 paper, 2025). A melanoma derived from melanocytes of the uveal tract. "In uveal melanoma (UVM), PDCL3 expression was positively correlated with five immune cell types (Th cells, Tcm, Th2 cells, Tem, and T gamma delta cells [Tgd]) but negatively correlated with five others (Th17 cells, pDC, NK cells, NK CD56bright cells, and Mast cells)." (PMID 40709189, 2025).